CRISPLD2 (cysteine rich secretory protein LCCL domain containing 2)
Diseases named in the same sentence as CRISPLD2 in open-access papers (continued):
Sharing a sentence is not in itself a finding about the gene and the disease.
adenocarcinoma (1 paper, 2013). A common cancer characterized by the presence of malignant glandular cells. "Of the 152 predicted gene targets in mouse and human genomes, four were significantly regulated in laser dissected lung dysplasia (AZIN1, CHST1, CRISPLD2 and FOXQ1) while 11 genes were significantly regulated in laser-dissected adenocarcinomas." (PMID 24265725, 2013). "In the case of RECK, CRISPLD2, HPGD, GATA3 and GPC3, the signal related to the expression of the protein was down regulated in more than 45% of adenocarcinomas compared to surrounding healthy pneumocytes." (PMID 24265725, 2013).
infection (1 paper, 2013). The state of being infected such as from the introduction of a foreign agent such as serum, vaccine, antigenic substance or organism. "The CRISPLD2 level might potentially reflect the host’s response to infection, where the failure to upregulate CRISPLD2 expression indicates that the infection has entered a severe stage and/or is out of control (such as is observed in patients with septic shock or high PCT levels)." (PMID 23799041, 2013). "In addition, age, sex, comorbidities, sources and sites of infection did not affect the CRISPLD2 level." (PMID 23799041, 2013).
inflammation (1 paper, 2016). Aberrant reaction of the microcirculation characterized by movement of fluid and leukocytes from the blood into extravascular tissues. "It is also important to note that if CRISPLD2 has antiinflammatory effects – even if it is not a primary inducer of inflammation in COPD – it may still have potential as a broad‐spectrum therapeutic agent in the treatment of lung inflammation in COPD and other lung pathologies." (PMID 27597766, 2016).
lip (1 paper, 2013). "CRISPLD2 plays a role in the development of rat lung and mouse kidney and is also involved in the development of nonsyndromic cleft lip with or without cleft palate." (PMID 23799041, 2013).
neurodegenerative disease (1 paper, 2022). A disorder of the central nervous system characterized by gradual and progressive loss of neural tissue and neurologic function. "In addition, CRISPLD2 was found to be associated with several neurodegenerative diseases, but the specific mechanism is not certain." (PMID 36034287, 2022).
CRISPLD2 also shares sentences with these, for which no sentence is quoted: chronic pancreatitis (2 papers); hepatocellular carcinoma (2); bacterial infection (1); cardiac ischemia (1); cardiovascular disease (1); carotid atherosclerosis (1); chronic myelogenous leukemia (1); colorectal cancer (1); endometrial cancer (1); Hepatic fibrosis (1); Hepatic steatosis (1); Huntington disease (1); Infertility (1); ischemic heart disease (1); lung adenocarcinoma (1); meningioma (1); myocardial infarction (1); nonalcoholic fatty liver disease (1); Obesity (1); ovarian carcinoma (1); Ovarian cyst (1); pancreatitis (1); Parkinson disease (1); primary immunodeficiency (1).